ARL6IP6 (ARF like GTPase 6 interacting protein 6)
Synonyms: Aip-6; PFAAP1; MGC33864; AIP6
Tractability: Antibody: UniProt predicts a signal peptide or a membrane-spanning region. PROTAC: its protein half-life has been measured.
Gene: Protein-coding gene on chromosome 2 (152,717,647 to 152,762,396, forward strand). Ensembl gene ENSG00000177917.
Subcellular location: Nucleus inner membrane
Subcellular location (Human Protein Atlas): Nuclear membrane; Cytosol
Gene Ontology:
Molecular function: protein binding
Cellular component: nuclear inner membrane
Genetic constraint (gnomAD): Loss-of-function variants: 22 observed, 21.96 expected, observed/expected ratio (o/e) 1, 90% interval 0.71 to 1.43. The synonymous counts are far from expectation, so gnomAD's model fits this gene poorly and the ratio says little. Missense variants: 388 observed, 313.44 expected, observed/expected ratio (o/e) 1.24, 90% interval 1.14 to 1.35. Synonymous variants: 164 observed, 127.81 expected, observed/expected ratio (o/e) 1.28, 90% interval 1.13 to 1.46.
Homologues: Orthologues: chimpanzee ARL6IP6 (99% identical), macaque ARL6IP6 (95% identical), pig ARL6IP6 (86% identical), rabbit ARL6IP6 (86% identical), mouse Arl6ip6 (82% identical), dog ARL6IP6 (77% identical), rat Arl6ip6 (68% identical), tropical clawed frog arl6ip6 (42% identical), zebrafish arl6ip6 (26% identical).
Diseases named in the same sentence as ARL6IP6 in open-access papers:
ARL6IP6 is named in the same sentence as 10 diseases in open-access papers, as found by Europe PMC text mining. Sharing a sentence is not in itself a finding about the gene and the disease. The quoted sentences say what the papers report.
ischemic stroke (4 papers, 2012 to 2021). A stroke disorder caused by obstruction of blood flow to the brain, due to thrombotic (local blood clot formation) or embolic (due to a blood clot or other material traveling from another site) event. "ARL6IP6 (MIM 616495) is an ADP-Ribosylation-Like Factor 6 Interacting Protein 6, associated with ischemic stroke." (PMID 34452458, 2021). "The consequence of the ARL6IP6 gene mutation remains unknown, although it is thought to be a genetic susceptibility factor for younger patients with ischemic stroke." (PMID 31801575, 2019).
Stroke (2 papers, 2011 to 2019). Sudden impairment of blood flow to a part of the brain due to occlusion or rupture of an artery to the brain. "Although no single SNP reached genome-wide significance (P < 5 × 10−8), we identified two SNPs in chromosome 2q23.3, rs2304556 (in FMNL2; P = 1.2 × 10−7) and rs1986743 (in ARL6IP6; P = 2.7 × 10−7), strongly associated with early-onset stroke." (PMID 22384361, 2011). "A similar association with stroke risk was observed for a nearby SNP, rs1986743, located on ARL6IP6, although the strength of association for this SNP diminished substantially after adjusting for rs2304556, suggesting the two SNPs may not represent independent signals." (PMID 22384361, 2011). "Two other studies have reported autosomal recessive inherited homozygous mutations in the ARL6IP6 gene in patients with CMTC and stroke." (PMID 31801575, 2019).
developmental delay (1 paper, 2024). "ARL6IP6 loss-of-function mutations have also been identified as a possible cause of cutis marmorata telangiectatica congenita, presenting with major dysmorphism, developmental delay, transient ischemic attacks, and cerebral vascular malformations." (PMID 38534785, 2024).
neurodegenerative disease (1 paper, 2024). A disorder of the central nervous system characterized by gradual and progressive loss of neural tissue and neurologic function. "Mutations of the ARL6IP6 gene, undergoing reduced expression in almost all neurodegenerative types/subtypes of MPS, have been found in many other neurodegenerative diseases." (PMID 38534785, 2024).
tumours (1 paper, 2023). "Among the dark genes, we found that patients with tumours with high expression of ARL6IP6 exhibited the shortest significant OS duration (OS = 57.07 months) compared to those with low gene expression (OS = 127.33 months)." (PMID 38117798, 2023). "We observed that DFS periods were significantly shorter (log-rank test; p = 9.44 x 10−13) for patients with tumours expressing high ARL6IP6 levels than those with low ARL6IP6 expression." (PMID 38117798, 2023).
ARL6IP6 also shares sentences with these, for which no sentence is quoted: Ataxia (1 paper); HCMV infection (1); Hypertension (1); melanoma (1); transient ischemic attack (1).